SOX2 (SRY-box transcription factor 2)
Diseases named in the same sentence as SOX2 in open-access papers (continued):
Sharing a sentence is not in itself a finding about the gene and the disease.
cancer (continued). "Potential relationships with the expression of tumoral PD-L1 and cancer stem cell (CSC) markers (NANOG, SOX2, OCT4, Nestin and Podoplanin (PDPN)) are assessed." (PMID 34201050, 2021). "In our previously published studies we showed that YB1 is required for the regulation of cancer stem cell phenotypes by modulating the expression levels of cancer stem cell (CSC) transcription machinery, including Oct4, Sox2, and Nanog." (PMID 34944882, 2021). "We also found strong correlations between MES and ADRN TFs with markers of cancer cell stemness and cancer cell motility including CDH1, CDH2, NANOG, SOX2, TWIST1, VIMENTIN, and Fibronectin across cancers." (PMID 35201514, 2021). "As our GSC models grown in-vitro are typically SOX2+/BTK−, this indicates that these in-vitro cell models are representative of the dominant SOX2+ cancer cell population in-vivo." (PMID 34645618, 2021). "This would open a window of opportunity for developing anti-cancer drugs targeting LSD1 and through it, cancer cells with high SOX2." (PMID 33572108, 2021). "The effects of combination of DSF and Galunisertib on the self-renewal ability, the expression of cancer stem cell markers (such as CD133, SOX2, and NANOG), and the ability for differentiation into multiple cell types are necessary." (PMID 34638842, 2021). "Meanwhile, EMT confers metastatic and cancer stem cell properties, such as Sox-2, Oct-4, and CD133 to cancer cells and is always correlated with poor clinical outcomes for cancer patients with malignant transformation stage." (PMID 34885925, 2021). "The Shh pathway stimulates CSC self-renewal of a variety of cancers by inducing the expression of several stemness-related genes, including c-MYC, BMI1, Nanog, SOX2, and OCT4." (PMID 33499351, 2021). "SOX2 and OCT4 are stem cell predictor factors that induce the expression of each other, regulate cancer progression, and are biomarkers of CSCs." (PMID 34803458, 2021). "Sex-determining region Y-box 2 (SOX2) is a stem cell transcription factor and a major regulator of self-renewal and pluripotency of cancer stem cells (CSCs)." (PMID 34436030, 2021). "Cancer cells expressing SBSN display stem markers and indeed, SOX2 is currently the only identified transcription factor known to promote SBSN expression specifically in ESCC." (PMID 33477529, 2021). "Many self-renewal regulatory factors, such as OCT4, SOX2, BMI, and NANOG, are expressed in human malignant tumors, and they play an important role in carcinogenesis." (PMID 33925224, 2021). "It was recently found that the replication of HBV is positively correlated to the expression of cancer stemness markers (EpCAM, CD44, CD133, NANOG, OCT4, and Sox2), tumorigenesis, and self-renewal." (PMID 33669204, 2021). "While the fusion protein was found to modulate SOX2 expression, a CD133 subpopulation with cancer stem cell properties was identified." (PMID 34573355, 2021). "MYC, SOX2, JUN, or ARNT was significantly correlated with THBS2 in most cancers, including COAD and PAAD." (PMID 34804159, 2021). "Treatment of vHCC with momelotinib reduced the expression of cancer stemness markers, such as CD133, KLF4, and SOX2, and decreased ALDH1 activity, suppressing tumorsphere and colony formation of HCC cells." (PMID 34199353, 2021). "Cancer stemness markers (ALDH1, CD44, OCT-4, and SOX-2) highly increased when comparing to the cell subpopulation with low ALDH1 expression (ALlow)." (PMID 34163000, 2021). "CD44, ABCG2, Nanog, SOX2, and Oct4 were identified as important stem-cell transcription factors or markers involved in maintaining the CSC-like phenotypes in many kinds of cancer." (PMID 33596919, 2021). "Sox2 is one of a suite of genes that regulate the osteoblast lineage from its multipotent MSC lineage, and thus also has a role in cancers that originate from dysregulation in this lineage." (PMID 34201496, 2021).
cancer (continued). "Mechanistic investigations identified through the NFATc2/SOX2/ALDH1A1 axis, oxidative stress induced by cancer drug treatment is attenuated, leading to increased resistance in a mutation-independent manner." (PMID 34187410, 2021). "There is a direct relationship between the expression of OCT4B1 and stemness-related genes (OCT4, SOX2, NANOG, and KLF4), and its downregulation in cancer cell lines inhibits the expression of these genes[24 ▶]." (PMID 32429647, 2020). "On the basis of previous studies of NANOG regulators in various cancers, we chose the following protein regulators for further analysis: AGR2, KLF4, NOTCH1, OCT4, and SOX2." (PMID 32733958, 2020). "Although abnormal activation of MAPK signaling is an important factor in cancer progression, DUSP6 influenced stemness by upregulating ALDH1, Nanog, SOX2 and Oct4A and promoted self‐renewal." (PMID 32159851, 2020). "Using immunofluorescence analysis, the protein expression of Nestin, Sox2, Vimentin, and GFAP was analyzed in these primary cancer cell lines." (PMID 32742192, 2020). "QGP-1 spheroid cells exhibited cancer stem cell-like features, including expression of stem cell markers such as OCT4, SOX2, and CD24." (PMID 33182509, 2020). "This, in turn, induces expression of core stem cell genes NANOG, SOX2 and POU5F1, leading to increased cancer stemness and tumorigenic potential." (PMID 32235004, 2020). "Since we found that USP38 suppressed mRNA levels of cancer stem cell related genes, we next analyzed the mRNA half-life of CD133, SOX2, and NANOG to gain further insights into USP38 mediated regulation of gene transcripts." (PMID 32404892, 2020). "A recent study revealed that TM4SF1 overexpression increases the expression of SOX2 and NANOG, sustains the manifestation of cancer stem cell traits, and drives metastatic reactivation in the lung and brain." (PMID 33153498, 2020). "In monolayer cells, the expression of the cancer stemness marker CD24 was relatively concentrated on the membrane in spheroid cells and SOX2 expression was mostly confined in the nucleus." (PMID 32457900, 2020). "In this cohort, Sox2 and AR had independent and opposite effects on DMFI, DFI and cancer-specific survival, which triggered the analysis of FMC subgroups according to Sox2 and AR expression." (PMID 33553286, 2020). "For most cancers including PDAC, SOX2 expression has also been detected at the protein level by immunohistochemistry." (PMID 32457900, 2020). "The pluripotency factors NANOG, SOX2, and OCT4 have been reported as CSC markers and key regulators in HNSCC and other cancers." (PMID 32635524, 2020). "SRY-Box transcription factor 2 (SOX2), one of the stemness factors, has been demonstrated to aggravate therapeutic resistance and promote invasion and metastasis in several cancer types." (PMID 32756339, 2020). "Earlier studies have established a mechanistic link between expression of the transcription factor Sox2 and FGF or TGF-β signaling in osteoblasts or cancer cells, respectively." (PMID 32236725, 2020). "In our previous report, we also demonstrated that spheroids are enriched with cancer stem cells by showing the elevation of many stem cell markers, ALDH1, CD133, CD24, and SOX2 that is in line with our current study." (PMID 32046751, 2020). "Compared with CD83-OV and control groups, CD83-KD cancer cells showed a reduction of stemness factors, including KIT, CD44, and SOX2." (PMID 32823589, 2020). "Cancer stem cells play pivotal role in malignant cells transformation.Reprogramming genes, such as Nanog, KLF4, EpCAM, c-Myc, Sox2 andp-Oct4 induce the origin of CSCs." (PMID 32779438, 2020). "Cancer stem cells (CSCs) expressing stem cell markers (e.g., CD133, CD44) and transcription factors (e.g., OCT3/4, SOX2, KLF4, c-MYC) have been identified to exhibit undifferentiated (stem cell-like) and tumorigenic properties." (PMID 32389123, 2020).
cancer (continued). "Taken together, the data suggested CAMK2A mediated in vitro cancer phenotypes and drug resistance through reducing EZH2 and release of SOX2 from epigenetic repression." (PMID 32483123, 2020). "HER3 promoted the activation of signal transducer and activator of transcription 3 (STAT3) resulting in upregulation of the STAT3 target gene SRY-Box Transcription Factor 2 (SOX2) and survival of the cancer cells." (PMID 33327495, 2020). "The expression levels of cancer stemness markers, NANOG, OCT4, and SOX2, were significantly downregulated by stattic in FOXD2-AS1-overexpressing cells and vector cells." (PMID 31959918, 2020). "Currently, the specific properties of CSC were identified like high ALDH1 activity (aldehyde dehydrogenase 1), side population, chemo-resistance, and other CD molecules (CD44, CD133) or markers (SOX2, OCT4, NANOG, LGR5) positive in cancer." (PMID 32854760, 2020). "Knocking out Sox2 in CDK1-overexpressed cells can significantly inhibit CDK1; hence, the CDK1-Sox2 interaction is a potential therapeutic target in cancer." (PMID 32964032, 2020). "We also observed the decreased expression of several cancer stemness genes, including BMI1, Oct4, and Sox2, which maintain breast CSCs 27-29." (PMID 32922184, 2020). "It has been reported that the transcription factor complex of POU5F1, SOX2, and KLF4 binds to the Nanog promoter to induce cellular reprogramming and cancer stemness." (PMID 32978904, 2020). "These target genes include cancer stemness genes (e.g., sex-determining region Y-box 9 (SOX9), fibroblast growth factor 19 (FGF19), and SOX2), cytokines, and their receptor genes (e.g., interleukin-8 (IL-8) and IL-1 receptor, type II (IL-1R2))." (PMID 32859041, 2020). "Genomic profiling of ESCC tumors found 98% patients having amplification in one or more cancer‐relevant genes, as well as the co‐amplification of genes at adjacent chromosome locations, such as CCND1/FGF19 and TERC/SOX2/PIK3CA." (PMID 31851786, 2020). "SOX2, OCT4, and NANOG are overexpressed in poorly differentiated malignant tumors and their expression overlaps with the characteristics of embryonic stem cells." (PMID 32766132, 2020). "Further underscored by findings in human cancer cells, PI3K/AKT signaling sustains nuclear entry and DNA modulatory functions of SOX2, whereas in AKT-inhibited cells, SOX2 is retained in the cytosol and is successively cleared by proteasomal turnover." (PMID 32664542, 2020). "Our study substantiates a novel mechanism by which TM4SF1 maintains cancer cell stemness and EMT via the Wnt/β-catenin/c-Myc/SOX2 axis during the recurrence and metastasis of CRC." (PMID 33153498, 2020). "Transcription factors, which play a critical role in reprogramming cells to pluripotency have also been identified in human cancers, including PCa and include POU5F1, SOX2 and ALDH160." (PMID 32647229, 2020). "In this study, morusin treatment was shown to decrease the expression of Oct4, SOX2, ALDH1, as well as epithelial-to-mesenchymal markers, thereby decreasing the stemness signature of the cancer cells." (PMID 32906784, 2020). "EMT and cancer stem cell (CSC) phenotype are closely related, therefore, we also checked the effect of let-7c on CSC phenotype by assessing CSC marker, SOX2." (PMID 32641854, 2020). "ZIC2, as transcription factor (TF), behaved as the other core pluripotent TFs (SOX2, NANOG, c-MYC) in cancer stem cells." (PMID 32922547, 2020). "It has been shown that Oct4, SOX2 and SOX17 mutants are able to dimerize, forming heterodimers that contribute to tumorigenesis across different cancers." (PMID 33152990, 2020). "As further proof, our data on downregulation of stemness-related markers, ALDH2 and SOX2, provides additional support for the activity of SNG against cancer stem-like cells." (PMID 32182833, 2020). "Considering the intimate connection between EMT and cancer stemness, we further examined the expression of six key biomarkers of cancer stemness (NANOG, SOX2, OCT4, CD44, ABCG2, BMI1)." (PMID 32863941, 2020).
cancer (continued). "Expression levels of cancer stem cell markers (CD44, CD133, SOX2, OCT3/4, and NANOG) were also decreased after silencing of SKIL in CALU-3 and NCI-H520." (PMID 33268765, 2020). "We were interested in the effect of CAFs on Sox2 (sex determining region Y (SRY)-box 2), which not only is an essential embryonal stem cell transcription factor, but also plays a role in cancer stem cell activity." (PMID 33228022, 2020). "Normal stem cells and cancer stem cells share some core stemness transcription factors such as OCT4, SOX2, and Nanog." (PMID 31375149, 2019). "As CSCs overexpress SOX2, POU5F1, and NANOG, it is suspected that reprogramming of cancer cells is mediated via overexpression of those transcription factors." (PMID 30382472, 2019). "We investigated the ALDHhigh/low populations in both histotypes for the mRNA expression of SOX2 and NANOG, which are stemness-related genes in normal and cancer cells." (PMID 31921651, 2019). "Thiostrepton treatment not only inhibited CSC markers including CD133, Oct‐4A and Sox2, but also restored E‐cadherin expression, thereby reversing the EMT and generation of cancer spheres." (PMID 31638335, 2019). "RASAL2 also downregulates sex-determining region Y-box 2 (SOX2) and CD44, which are indicators of cancer stemness, by inhibiting the ERK/MAPK pathway." (PMID 31799194, 2019). "Aberrant PI3K-mTOR signalling was shown to also regulate the properties of key cancer stem cell (CSC) factors, including the sex determining region Y box 2 (SOX2)." (PMID 30970654, 2019). "It is evident that the core stem cell factors OCT4, SOX2, and NANOG play essential roles in maintaining the pluripotency and self-renewal of embryonic stem cells, adult stem cells, and cancer stem cells." (PMID 31375149, 2019). "First, both the SOX2 and ST6GAL1 genes are extensively amplified, but rarely deleted, across multiple cancer types." (PMID 31610800, 2019). "In some somatic cancers, the dysregulation of SOX2OT expression and its concomitant expression with SOX2 has become a prominently observed phenomenon, and SOX2OT plays a key role in pluripotency and tumorigenesis." (PMID 31827385, 2019). "Next, to assess the effect of DFX and CDDP on cytotoxicity and expression of stemness markers in human cancer cell lines, we used HSC-2 cells and OE33 cells, which express similar stemness markers (Nanog, Sox2, Oct3/4, Klf4, c-Myc) as ES cells." (PMID 30717462, 2019). "In cancer stem cells, many transcription factors, especially OCT4, NANOG, and SOX2, are overexpressed, a pattern common to that in early embryonic stem cells." (PMID 31375149, 2019). "It has been reported that pluripotent cancer cells with microRNA-302s transfection exhibit decreased tumorigenicity, genomic demethylation, and elevated expressions of SSEA-3/4, SOX2, NANOG, and Oct-3/4." (PMID 31464654, 2019). "GLI1 enhances cancer stem cell properties by upregulating stem cell markers like OCT4, Nanog, and SOX2." (PMID 31492002, 2019). "The m6A mRNA methyltransferase METTL3 is upregulated in multiple types of cancers and can promote the m6A modification and expression of oncogenes including EGFR, TAZ, MYC, and SOX2." (PMID 30796352, 2019). "To evaluate the interaction between LETM1 expression and the stem cell like characteristics of LETM1 positive cells, we analyzed and compared its expression with that of other cancer stemness-related genes such as CD44, LSD1, Sox2 and Sox9." (PMID 31500591, 2019). "miR-145 actsas a tumor suppressor molecule in a lot of cancers.miR-145 inhibits endometriotic cell proliferation, andself-renewal via targeting OCT4, KLF4, and SOX2 andinduces hESC and CSCs differentiation." (PMID 30825291, 2019). "The SORE6 reporter was constructed using 6 tandem repeats of the SOX2 and OCT4 response element from the proximal human NANOG promoter and has been used to detect breast CSCs, but for other types of cancer its utility remains to be investigated." (PMID 31500347, 2019).
cancer (continued). "The CSC markers SOX2, OCT4, and Nanog have been demonstrated to promote the resistance of cancer to drugs including sorafenib, tamoxifen, cisplatin, and paclitaxel." (PMID 30657254, 2019). "YAP silencing reduced the expression of stem cell-related markers (CD133, Nanog, Sox2), as well as sphere-forming ability of rhHMGB1 stimulated CD133− cancer cells, confirming its role in cancer cell stemness." (PMID 31558702, 2019). "Anti-cancer effect of AC acting on CSC’s was related with reduced expression of cancer stem cell markers such as β-catenin, SOX-2, and Nanog (stemness marker) in comparison to control." (PMID 31349708, 2019). "Overexpression of the other four (SOX2, POU3F2, OCT-4, and OLIG1) or five (SOX2, SALL2, OCT-4, POU3F2, and Bmi-1) transcription factors in YB-1 knockout cancer stem cells generated similar results." (PMID 31375149, 2019). "There is growing evidence that SOX2 expression is highly correlated with resistance mechanisms and epithelial-mesenchymal transition (EMT)-specific gene expression in cancers." (PMID 30382472, 2019). "It has been widely reported that the epithelial-to-mesenchymal transition (EMT)- and stemness-related genes including Slug, KLF4, SOX2, OCT4, and NANOG are overexpressed in human cancers and confer CSCs traits." (PMID 31526394, 2019). "To conclude, we analyzed the influence of CPEB1 on cancer stemness in HCC cells by analyzing self-renewal ability, chemoresistance, metastasis and expression of the stem cell-related genes OCT4, NANOG, SOX2, LIN28, CD24, EpCAM and CD133." (PMID 30237545, 2018). "We conclude that BRACHYURY and SOX2 synergistically promote EMT (invasiveness) and self-renewal property, and one of the members of cancer stemness related genes." (PMID 30453543, 2018). "A Cancer Stem Cell Transcription Factor Activation Array (Signosis, Inc, number FA-1004) also found KLF4, MYC, NANOG, OCT-3/4, SOX-2 and SNAIL activated in both MCF-7 and T47D after treatment with the CM of HA-BrC cells (data not shown)." (PMID 29928478, 2018). "As above reported, the amplification of chromosome 3q26 results in the co-amplification and co-expression of protein kinase C iota (PKCι) and SOX2 in LSQCC which cooperate to trigger and maintain cell-autonomous HH signaling in LSQCC cancer stem cells." (PMID 30060526, 2018). "Leptin also induces the expression of TFs associated with the maintenance of the cancer stem cell phenotype, such as NANOG, SOX2, and OCT4 in a STAT3-dependent manner, promoting a more aggressive phenotype of cancer cells." (PMID 30404206, 2018). "Some of the players found to be affiliated with EMT and cancer stem-like cell maintenance include the PI3K/AKT pathway, RhoA, VEGFR, SOX2 and Wnt/β-catenin and SHH pathways." (PMID 29298329, 2018). "c, Expression levels of markers related to cancer stem cells [nanog homeobox (NANOG) and SRY (sex determining region Y)-box 2(SOX2)] was assessed by western blot assay in both enriched spheres (SP) and monolayer parental cells (2D)." (PMID 30231942, 2018). "In this cancer type, the Wnt/β-catenin/MYC/Sox2 axis is an important regulator of cancer cell plasticity." (PMID 29609590, 2018). "By determining the optimal cut-off using ROC curves for each molecule, the individual sensitivity and specificity of these six molecules (NANOG, CD49f, LGR5, ΔNp63, SOX2, and CD24) for cancer detection ranged from 29.2% to 62.5% and 83.3 to 100%, respectively." (PMID 30327565, 2018). "This implies that through OCT4, KLF4, NANOG, and SOX2 alteration, KRT19 regulates cancer stem cell reprogramming efficiency in KU-CSLCs." (PMID 29747452, 2018). "In other words, the closer to the centre of the network (SOX2 and BRACHYURY) a target factor is, the greater the impact of its inactivation on EMT and cancer stemness." (PMID 30453543, 2018). "On co-treatment, cancer stem cell genes (OCT4, SOX2 and NANOG) were found to be down-regulated, which indicated the elimination of the NB-cancer stem cell properties." (PMID 29774131, 2018).